ZMYM1 (zinc finger MYM-type containing 1)
Synonyms: FLJ23151; MYM
Tractability: PROTAC: UniProt records ubiquitination sites on it; ubiquitination databases record sites on it.
Gene: Protein-coding gene on chromosome 1 (35,032,172 to 35,118,818, forward strand). Ensembl gene ENSG00000197056.
Subcellular location: Nucleus
Subcellular location (Human Protein Atlas): Centriolar satellite; Nucleoplasm
Gene Ontology:
Molecular function: protein dimerization activity; zinc ion binding
Cellular component: nucleus
Genetic constraint (gnomAD): Loss-of-function variants: 37 observed, 72.09 expected, observed/expected ratio (o/e) 0.51, 90% interval 0.39 to 0.68. The upper end of that interval is the gene's LOEUF score, 0.68, which puts it in group 2 of 6, group 1 being the genes least tolerant of losing a copy. Missense variants: 1,140 observed, 1,318 expected, observed/expected ratio (o/e) 0.86, 90% interval 0.82 to 0.91. Synonymous variants: 402 observed, 459.62 expected, observed/expected ratio (o/e) 0.87, 90% interval 0.81 to 0.95.
Homologues: Orthologues: chimpanzee ZMYM1 (99% identical), macaque ZMYM1 (97% identical), rabbit ZMYM1 (81% identical), pig ZMYM1 (81% identical), dog ZMYM1 (78% identical), guinea pig ZMYM1 (77% identical), rat Zmym1 (55% identical), mouse Zmym1 (55% identical), zebrafish si:ch211-240b21.2 (5% identical). Paralogues in human: ZMYM4 (29% identical), ZMYM6 (25% identical), ZMYM2 (19% identical), ZMYM3 (18% identical), ZMYM5 (10% identical), QRICH1 (9% identical), GTF2IRD1 (6% identical), THAP12 (5% identical), GTF2I (5% identical), ZBED11 (5% identical), GTF2IRD2 (5% identical), GTF2IRD2B (5% identical), and 6 more.
Diseases named in the same sentence as ZMYM1 in open-access papers:
ZMYM1 is named in the same sentence as 7 diseases in open-access papers, as found by Europe PMC text mining. Sharing a sentence is not in itself a finding about the gene and the disease. The quoted sentences say what the papers report.
gastric cancer (20 papers, 2019 to 2025). A primary or metastatic malignant neoplasm involving the stomach. "For example, METTL3 is a key promoter of gastric cancer metastasis in vivo and malignant progression in vitro, activating downstream regulatory networks through regulation of m6A-dependent ZMYM1." (PMID 37344779, 2023). "In contrast, METTL3 overexpression elevates m6A methylation in ZMYM1 mature mRNA, stabilizes ZMYM1 mature mRNA, and enhances its protein expression level, thus promoting invasive metastasis of gastric cancer." (PMID 38102645, 2023). "ELAVL1 stabilizes ZMYM1 mRNA in an m6A-dependent manner, enhancing gastric cancer progression by facilitating the transition from epithelial to mesenchymal tissue." (PMID 36348434, 2022). "Especially, with regard to EMT process, several articles demonstrated the important roles of m6A regulation on SNAI1 in HeLa and HepG2 cells, GFI1 and ZMYM1 in gastric cancer cells, AXL in ovarian cancer cells, and ZBTB1 in bronchial epithelial cells." (PMID 36183833, 2022). "For instance, METTL3 can exacerbate EMT in gastric cancer by activation of the zinc finger MYM-type containing 1 signaling, while it can also upregulate the JunB proto-oncogene to mediate the progression of EMT in lung cancer." (PMID 34666602, 2021). "The Zmym1 gene has been reported to promote epithelial-to-mesenchymal transition and metastasis, cell growth and migration by inhibiting E-cadherin expression in gastric cancer." (PMID 38660676, 2024). "In gastric cancer, the enhancement of ZMYM1 mRNA stability by METTL3 was similarly dependent on its m6A catalytic activity, and enrichment of ZMYM1 could initiate the EMT procedure." (PMID 38221933, 2024). "EMT process was facilitated by stable ZMYM1 through up-regulation of METTL3 in gastric cancer." (PMID 34116604, 2021). "For example, METTL3-mediated m6A methylation enhanced ZMYM1 mRNA expression in gastric cancer." (PMID 33251217, 2020). "In gastric cancer, METTL3-mediated m6A modification enhances the stability of ZMYM1 mRNA and increases the expression of ZMYM1, thus facilitating epithelial-mesenchymal transition (EMT) and metastasis." (PMID 37231451, 2023). "In gastric cancer, aberrant METTL3 has long been recognized as a marker of poor patient prognosis, and enhanced METTL3 up-modulated m6A modification of ZMYM1 mRNA, DEK mRNA or HDGF mRNA to induce tumor growth and distant metastasis." (PMID 37344779, 2023). "For example, in gastric cancer, METTL3 promotes the pathogenesis by catalyzing the methylation of ZMYM1 or HDGF." (PMID 34489709, 2021). "In gastric cancer (GC), METTL3 can cause m6A to accumulate on HDGF mRNA, which indicates proliferation and poor prognosis and enhances the stability of zinc finger MYM-type containing 1 (ZMYM1) mRNA so that it accelerates epithelial-mesenchymal transition (EMT) and metastasis." (PMID 32303268, 2020). "Referring to studies of downstream targets regulated by METTL3 in tumours, it has been reported that in gastric cancer, METTL3 promotes ZMYM1 mRNA stability through m6A modification, subsequently enhancing its protein expression through the m6A reader protein HuR (also known as ELAVL1)." (PMID 38238831, 2024). "Mechanically, Mettl3 could activate zinc finger MYM-type containing 1 (ZMYM1) toward genes complex of chromatin via m6A modification, hence promoting epithelial–mesenchymal transition (EMT) and metastasis of gastric cancer." (PMID 33681207, 2021). "In gastric cancer (GC), overexpression of METTL3 can promote the stability of ZMYM1, thereby enhancing epithelial mesenchymal transformation (EMT) process and tumor metastasis." (PMID 33015074, 2020).
tumor (4 papers, 2023 to 2024). "It was reported that METTL3 regulates HDGF in an m6A-mediated manner to promote tumor angiogenesis and glycolysis and also regulates ZMYM1, SPHK2, and MYC to promote GC tumor metastasis." (PMID 39195675, 2024). "ELAVL1 promotes the expression of certain tumor-related genes, such as ZMYM1 and DRG1, in an m6A-dependent manner, thereby exerting pro-carcinogenic effects." (PMID 37744335, 2023).
cancer (3 papers, 2019 to 2023). A tumor composed of atypical neoplastic, often pleomorphic cells that invade other tissues. "For example, in GC, METTL3 can promote cancer by catalyzing the methylation of either ZMYM1 or HDGF." (PMID 32398132, 2020). "Furthermore, in GC, higher expression of METTL3 promotes cancer cell metastasis in vivo and is predictive of poor prognosis in GC patients, which is possibly through the m6A modified stabilization of the zinc finger MYM-type containing 1 (ZMYM1) mRNA." (PMID 37015927, 2023).
ZMYM1 also shares sentences with these, for which no sentence is quoted: autoimmune disease (1 paper); leukemia (1); lung carcinoma (1); ovarian carcinoma (1).